ABCB4 (ATP binding cassette subfamily B member 4)
Diseases named in the same sentence as ABCB4 in open-access papers (continued):
Sharing a sentence is not in itself a finding about the gene and the disease.
Cholestatic liver disease (27 papers, 2011 to 2026). "Genetic variations of ABCB4 are associated with rare cholestatic liver diseases, the most severe being progressive familial intrahepatic cholestasis type 3, for which most of patients require liver transplantation before adulthood." (PMID 41735377, 2026). "Combined genetic, structural, and functional analyses are valuable tools for characterizing variants of uncertain significance in ABCB4-associated cholestatic liver disease." (PMID 41993931, 2026). "This study shows findings suggestive of liver involvement in 55.6% of volunteers, underscoring the potential of rare heterozygous ABCB4/11 variants as markers for identifying individuals at high risk of developing cholestatic liver disease." (PMID 41436587, 2025). "Our findings in this study suggest liver involvement in 55.6% of these cases emphasising the role of rare heterozygous ABCB4/11 variants as potential markers for identifying those at elevated risk of cholestatic liver disease." (PMID 41436587, 2025). "The liver histopathology of cholestatic liver disease associated with ABCB4 mainly involves bile duct changes such as epithelial damage, atrophy, and cholesterol lysis." (PMID 38610052, 2024). "Recently, with the in-depth study of the ABCB4 (ATP binding cassette, sub-family B, member 4) gene, cholestatic liver diseases caused by ABCB4 mutations have been increasingly recognized." (PMID 38610052, 2024). "As previously published, genetic polymorphisms within the ABCB4 locus are likely to affect the function of the phospholipid transporter, predisposing carriers for cholestatic liver diseases." (PMID 36397154, 2022). "We report a case of congenital MyoD with combined heterozygous ATP8B1/ABCB4 mutation who developed chronic, progressive low gamma-glutamyltransferase cholestatic liver disease at early infancy, and eventually underwent successful liver transplantation." (PMID 37206451, 2021). "ABCB4 missense mutations that prevent normal trafficking of ABCB4 to the canalicular membrane of the hepatocyte result in a complete loss of ABCB4 function, which leads to progressive cholestatic liver disease." (PMID 26900700, 2016). "ABCB4, also known as multidrug resistance P-glycoprotein 3, translocates phosphatidylcholine (PC) from the inner to the outer plasma membrane, thus functioning as a PC flippase; mutations in ABCB4 cause cholestatic liver disease." (PMID 21545734, 2011). "However, the genotype-phenotype relationship underlying ABCB4 gene-related cholestatic liver diseases still need further explored." (PMID 38610052, 2024). "ABCB4 defects are associated with several cholestatic liver diseases." (PMID 34209301, 2021). "In addition, the absence of TLR4 has protective effects against pre-cancerogenous events in cholestatic liver injury, pointing to new avenues for the prevention and therapy of cancer in ABCB4 deficiency and related cholestatic liver diseases." (PMID 27391331, 2016). "Null mutations in ABCB4 gene give rise to severe early-onset cholestatic liver disease." (PMID 26900700, 2016). "Genes involved in bile formation, such as ABCB4 (encodes canalicular phosphatidylcholine floppase) and ABCB11 (encodes bile salt export pump (BSEP)) have been associated with cholestatic liver disease 8–10." (PMID 41436587, 2025). "This study retrospectively analyzed the clinical and pathological characteristics of 23 patients with ABCB4 gene-related cholestatic liver diseases." (PMID 38610052, 2024). "All patients with ABCB4-related cholestatic liver diseases were treated with UDCA, glycyrrhein, glutathione, and butyldisulfonate methionine during hospitalization." (PMID 38610052, 2024). "Twenty-three Han Chinese patients were diagnosed with ABCB4-related cholestatic liver diseases from 21 families consisting of 15 children and 8 adults." (PMID 38610052, 2024). "In this study, the clinical and pathological characteristics of 23 patients with ABCB4-related cholestatic liver diseases were exhibited." (PMID 38610052, 2024).
Cholestatic liver disease (continued). "ABCB4 gene-related cholestatic liver diseases have a wide spectrum of clinical and genetic variations." (PMID 38610052, 2024). "Therefore, we investigated in this study ABCB11 and ABCB4 on RNA as well as protein levels in liver tissue of patients with different types of cholestatic liver diseases, with a special interest in PSC." (PMID 31886153, 2019). "Therefore, whether UDCA alters the natural history of ABCB4-related cholestatic liver diseases remains unclear." (PMID 38610052, 2024). "Genetic analysis using next-generation sequencing included a panel of five genes involved in cholestatic liver diseases (ATP8B1, ABCB11, ABCB4, ABCC2 and MYO5B)." (PMID 41797682, 2026). "In contrast, the staining pattern of ABCB11 and ABCB4 was mostly consistent in all PSC patients, when compared to patients with other chronic liver/cholestatic liver diseases." (PMID 31886153, 2019). "Increased expression of ABCB11 and ABCB4 was very consistent in PSC patients and not observed in other cholestatic liver diseases." (PMID 31886153, 2019).
cholelithiasis (26 papers, 2007 to 2025). The presence of crystallized deposits forming in the gallbladder or biliary tree, primarily composed of cholesterol, bilirubin, and bile. "Low-phospholipid-associated cholelithiasis (LPAC) syndrome is a recently described rare form of cholelithiasis that has been linked to the ATP-binding-cassette subfamily B, member 4 (ABCB4) gene deficiency." (PMID 36277956, 2022). "The low-phospholipid-associated cholelithiasis (LPAC) syndrome is a recently described peculiar form of cholelithiasis associated with the ATP-binding-cassette subfamily B, member 4 (ABCB4) gene deficiency." (PMID 36277956, 2022). "Low phospholipid-associated cholelithiasis (LPAC) is characterized by the association of ABCB4 mutations and low biliary phospholipid concentration with symptomatic and recurring cholelithiasis." (PMID 17562004, 2007). "Low phospholipid-associated cholelithiasis (LPAC) is characterized by the association of ABCB4 mutations with symptomatic and recurring cholelithiasis in young adults (e.g. <40 years)." (PMID 17562004, 2007). "In people, ABCB4 gene mutations are associated with several disease syndromes including intrahepatic cholestasis of pregnancy, progressive familial intrahepatic cholestasis (type 3), primary biliary cirrhosis, and cholelithiasis." (PMID 20598156, 2010). "We determined more generally the frequency of ABCB4 gene mutations in 60 consecutive adult patients who had been referred to our liver unit because of symptomatic or complicated cholelithiasis and we characterized more precisely the clinical phenotype associated with these mutations." (PMID 17562004, 2007). "Genes such as ABCG5/G8, ABCB4, ABCB11, and UGT1A1 are crucial in increasing the lithogenicity of bile and are strongly associated with various forms of cholelithiasis, especially cholesterol-based." (PMID 40149408, 2025). "ABCB4 defect is also involved in intrahepatic cholestasis of pregnancy (ICP), low-phospholipid-associated cholelithiasis (LPAC), and primary biliary cirrhosis." (PMID 25133187, 2014). "Analysing the entire MDR3 (ABCB4) gene coding sequences represents that MDR3 (ABCB4) gene mutations are a major genetic risk factor in a symptomatic and recurring form of cholelithiasis in young adults." (PMID 25107305, 2014). "ABCB4 genotyping should be used to confirm the diagnosis of LPAC syndrome in young adults who present with a symptomatic cholelithiasis and should allow familial screening." (PMID 17562004, 2007). "This is consistent with the spontaneous occurrence of cholelithiasis in Abcb4 knockout mice." (PMID 19823678, 2009). "However, at present, the literature data and our results did not allow to determine the frequency of ABCB4 mutations in the whole population of patients with cholelithiasis." (PMID 17562004, 2007). "It is noteworthy that in the ABCB4 mutant carrier group, 8/12 (67%) had a family history of biliary disease (ICP, cholelithiasis or cirrhosis)." (PMID 28924228, 2017).
Cirrhosis (26 papers, 2009 to 2025). A chronic disorder of the liver in which liver tissue becomes scarred and is partially replaced by regenerative nodules and fibrotic tissue resulting in loss of liver function. "The relationship between a pathogenic variant of ABCB4 and the progression towards fibrosis and cirrhosis of diseases such as PSC (primary sclerosing cholangitis) and PBC has been explored." (PMID 39984942, 2025). "In this study, one child with a homozygous mutation (c.1241G > T) was diagnosed with cirrhosis at 2 years of age, indicating the high pathogenicity of homozygous ABCB4 mutations." (PMID 38610052, 2024). "Among 303 cases of cirrhosis and 681 cancer cases four ABCB4 variants were identified (c.1865G>A, p.G622E; c.1333_1334delCT, p.L445Gfs*22; c.1529A>G, p.N510S; c.711A>T, p.I237=) associated with these liver-specific traits." (PMID 35884482, 2022). "Multivariate analysis demonstrated that both the ABCB4 c.711A > T polymorphism and patients' gender represent two independent determinants of cirrhosis in our cohort." (PMID 36397154, 2022). "On the other hand, a total of 22 patients in this cohort developed cirrhosis, and this risk was significantly modulated by the ABCB4 c.711A > T risk variant (OR = 5.65, P = 0.040 by Armitage's trend test)." (PMID 36397154, 2022). "Univariate regression analysis in patients from Szczecin demonstrated significant associations of cirrhosis with both ABCB4 c.711A > T and patients' gender." (PMID 36397154, 2022). "In adults, it has been reported that monoallelic PV or LPV variant in ABCB4 can be associated with CC and cirrhosis consistent with an attenuated phenotype of PFIC3." (PMID 35626323, 2022). "In the Warsaw PBC cohort, univariate and multivariate regression analysis showed significant associations of ABCB4 c.711A > T, as well as patients` age and gender with cirrhosis (all P < 0.05)." (PMID 36397154, 2022). "One patient diagnosed with Wilson disease who developed hepatic cirrhosis was identified as having a homozygous mutation in ABCB4." (PMID 33763395, 2021). "In both cohorts of patients with PBC, ABCB4 c.711A > T increased the risk of cirrhosis." (PMID 36397154, 2022). "In this case report, we describe a patient affected by LPAC syndrome with Child–Pugh type C cirrhosis, who was waiting for liver transplant and presented with a classical triad of KFS and mutation of ABCB4." (PMID 38135884, 2023). "We report here the long-term follow-up of a patient with PFIC3 resulting in decompensated cirrhosis at 11 years who successfully underwent living donor liver transplantation from his father, who carried the same ABCB4 homozygous mutation." (PMID 37575491, 2023). "Of the 26 women with a mutation in a biliary transporter (ABCB4, ABCB11, APT8B1, ABCC2), 12 (46%) had an established family history of biliary disease (ICP, cirrhosis or gallstones)." (PMID 28924228, 2017). "All young adult patients with occult cirrhosis should be tested for ABCB4." (PMID 37488596, 2023). "Population-based, genetic studies in Iceland have shown a significant association between the presence of certain polymorphic variants of the ABCB4 gene and the occurrence of primary cancers of the liver regardless of the existence of cirrhosis." (PMID 36277956, 2022). "Well-established phenotypes of ABCB4 deficit are progressive familial intrahepatic cholestasis type 3, low phospholipid-associated cholelithiasis (LPAC) syndrome, high gamma-glutamyl transferase intrahepatic cholestasis of pregnancy, chronic cholangiopathy, and adult biliary fibrosis/cirrhosis." (PMID 38135884, 2023). "However, in this cohort the presence of ABCB4 c.711A > T did not modulate the risk of cirrhosis during follow-up (P > 0.05)." (PMID 36397154, 2022). "In contrast to human beings, where HCC development is mostly based on hepatic cirrhosis, Abcb4−/−/HBsAg+/− mice displayed a high tumor development without underlying cirrhosis." (PMID 28881751, 2017).
gallstones (21 papers, 2007 to 2025). Solid crystalline precipitates in the biliary tract, usually formed in the gallbladder, resulting in the condition of cholelithiasis. "In another genetic study, the ABCB4 gene (encoding a multi-drug resistance protein 3 (MDR3) was evaluated in the pathogenesis of idiopathic gallstones." (PMID 36362164, 2022). "If LPAC is suspected in young (age < 40 years) patients with gallstones, genetic analysis of ABCB4 mutations and variants should be performed as early as possible." (PMID 35741809, 2022). "If LPAC patients with symptomatic gallstones undergo cholecystectomy, postoperative recurrence of gallstones must be prevented because the lithogenic state of bile remains due to ABCB4 mutations and variants." (PMID 35741809, 2022). "Previous association studies have reported a linkage of gallstone formation and point mutations in the ABCB4 gene encoding the phospholipid transporter MDR3." (PMID 19823678, 2009). "The GWAS revealed an association of missense and splice region variants in ABCB4 with gallstones." (PMID 35884482, 2022). "It has been shown that mutations in this gene increase the risk of developing gallstones in subjects under 40 years, mainly by inducing an ABCB4 deficiency that results in low biliary phosphatidylcholine concentrations, which is consistent with the spontaneous occurrence of cholecystolithiasis." (PMID 35207722, 2022). "In another study involving 35 children with idiopathic gallstones meeting the clinical criteria of LPAC, in only one case, a possibly pathogenic variant c.2318G > T of the ABCB4 gene was found." (PMID 36362164, 2022). "As a result, gallstones are spontaneously formed in ABCB4 KO mice on chow, as evidenced by a systematic microscopic and physical-chemical analysis of the biliary and gallstone phenotypes." (PMID 35741809, 2022). "This may explain the earlier onset and higher prevalence of gallstones in female ABCB4 KO mice compared with males." (PMID 35741809, 2022). "No participant with ABCB4 LoF variants was found to have gallstones." (PMID 41436587, 2025). "In an activated Mdr2 (an ortholog of human ABCB4 gene) mouse model for PFIC3, hydrophobic BAs toxicity induces liver injury such as in PFIC3 patients with cholangitis, ductular proliferation, periportal fibrosis, susceptibility to the formation of gallstones and HBCs occurrence." (PMID 35884482, 2022). "In fact, the homozygous ABCB4 mutations lead to the complete absence of the phospholipid transporter and no secretion of phospholipids into bile, which finally causes a decrease in the solubility of bile, and consequently, a greater predisposition to bile crystallization and gallstone formation." (PMID 35207722, 2022). "Nevertheless, recent data from sib pairs with gallstones and control do not support a link between ABCB4 and ABCB11 polymorphisms and gallstone formation in the large majority of patients." (PMID 25107305, 2014). "Moreover, induction of CYP3A4, SULT2A1, and UGT2Bs, along with stimulation of biliary excretion through MDR3 (ABCB4), may also enhance BA detoxification and counteract cholesterol-gallstone after FXRα activation." (PMID 30453651, 2018). "In contrast, HL in Western cohorts is generally non-infectious and may be secondary to gallstone migration, post-surgical biliary strictures, congenital anomalies (e.g., Caroli disease), or metabolic predispositions such as ABCB4 (MDR3) mutations that impair phospholipid secretion." (PMID 40428818, 2025).
hepatocellular carcinoma (15 papers, 2011 to 2025). A malignant tumor that arises from hepatocytes. "For functional characterization studies, plasmids, encoding ABCB4 wild-type and selected established mutant constructs, were expressed in human embryonic kidney (HEK-293T) and hepatocellular carcinoma (HepG2) cells." (PMID 32626542, 2020). "In addition, genomic studies suggest a link between ABCB4 dysfunction and possible hepatobiliary malignancies, and it has been reported that ABCB4 is frequently epigenetically silenced in hepatocellular carcinoma." (PMID 35741809, 2022). "Moreover, hepatocellular carcinoma and intrahepatic cholangiocarcinoma have been documented in patients with ABCB4/MDR3 mutations." (PMID 30148122, 2018). "To date, the binding of human FXR in primary human hepatocytes (PHHs) or hepatoma cell lines has been characterized to limited genes, including ABCB4 (ATP-binding cassette, sub-family B, member 4), ABCB11, FGF19 (fibroblast growth factor 19), ICAM1 (intercellular adhesion molecule 1), and NR0B2." (PMID 25198545, 2014).
liver cancer (15 papers, 2009 to 2025). An epithelial or non-epithelial malignant neoplasm that arises from the liver. "For example, a large-scale whole-genome study conducted on the Icelandic population identified missense SNP variants in ABCB4 to be associated with gallstone disease, liver cancer, liver cirrhosis, and other liver-specific traits." (PMID 30521023, 2018). "Mice deficient in Abcb4 develop liver cancer as a result of chronic inflammation." (PMID 28220208, 2017). "In humans, non-synonymous SNPs in ABCB4 have been identified in patients with liver cancer (cholangiocarcinoma)." (PMID 28220208, 2017).
familial intrahepatic cholestasis (14 papers, 2014 to 2025). An instance of intrahepatic cholestasis that is caused by an inherited modification of the individual's genome. "Mutations in the ATP8B1, ABCB11 and in the ABCB4 genes encoding ATP8B1, BSEP and MDR3 respectively, have been linked to progressive familial intrahepatic cholestasis." (PMID 36430444, 2022). "Genes associated with familial intrahepatic cholestasis (FIC) include ATP8B1 (FIC1), ABCB11 (FIC2), ABCB4 (FIC3), TJP2 (FIC4), NR1H4 (FIC5) and MYO5B (FIC6)." (PMID 33557414, 2021). "Progressive familial intrahepatic cholestasis (PFIC) is caused by variations in ATP8B1, ABCB11 or ABCB4 genes." (PMID 29973134, 2018).
cholangitis (13 papers, 2007 to 2024). An acute or chronic inflammatory process affecting the biliary tract. "The loss of intercellular BEC junctions in Abcb4−/− mice was almost normalized in Abcb4−/−/IL-13−/− mice, which is in line with studies showing the disruption of the tight junction-associated BEC barrier by Th2 signals in cholangitis and biliary atresia." (PMID 32846954, 2020). "Abcb4 knockout mice (lacking the multidrug resistance protein 3) develop a form of cholangitis similar to human PSC that is caused by impaired biliary phospholipid secretion." (PMID 31089130, 2019).